ATG4B (autophagy related 4B cysteine peptidase)
Diseases named in the same sentence as ATG4B in open-access papers (continued):
Sharing a sentence is not in itself a finding about the gene and the disease.
pneumonia (1 paper, 2021). An acute, acute and chronic, or chronic inflammation focally or diffusely affecting the lung parenchyma, caused by an infection in one or both of the lungs (by bacteria, viruses, fungi, or mycoplasma.). "Increases in ATG4B levels are accompanied by the induction of autophagy in pneumonia and fibrosis." (PMID 34022797, 2021).
rectal cancer (1 paper, 2023). A primary or metastatic malignant neoplasm that affects the rectum. "Moreover, radiotherapy was only treated for rectal cancer patients, which would inevitably require a larger patient cohort to examine the involvement of ATG4B or pS383/392-ATG4B in the prognosis of rectal cancer." (PMID 37038218, 2023).
Sepsis (1 paper, 2020). Sepsis is defined as life-threatening organ dysfunction caused by a dysregulated host response to infection. "ATG4B protein expression was elevated in sepsis+miR-34a antagomir group but decreased in sepsis+miR-34a agomir group compared with that in sepsis+NC antagomir group or sepsis+NC agomir group." (PMID 32903604, 2020).
steatosis (1 paper, 2021). Increased lipid within the cytoplasm of cells. "Within nutrient overload steatosis models, 13 different experiments were analyzed from 9 manuscripts which genetically modulated the expression of ATG7, ATG4B, ATG14, TFEB, FIP200, and ULK1." (PMID 33937257, 2021).
tongue SCC (1 paper, 2019). "In this study, we compared the ATG4B and phospho-Ser383/392-ATG4B protein levels between tumor tissues and adjacent normal tissues in buccal mucosal SCC (BMSCC) and tongue SCC (TSCC)." (PMID 31771238, 2019). "However, the clinical relevance of ATG4B and phospho-Ser383/392-ATG4B for OSCC remains unknown, particularly in buccal mucosal SCC (BMSCC) and tongue SCC (TSCC)." (PMID 31771238, 2019).
Wilson disease (1 paper, 2022). A very rare inherited multisystemic disease presenting non-specific neurological, hepatic, psychiatric or osseo-muscular manifestations due to excessive copper deposition in the body. "•Overexpression of ATG4B could reduce the formation of Mallory body in copper overload Wilson disease model." (PMID 35349929, 2022).
cancer (50 papers, 2015 to 2026). A tumor composed of atypical neoplastic, often pleomorphic cells that invade other tissues. "Targeting ATG4B, the key factor of autophagy progress, can inhibit cancer metastasis in vitro, but ATG4B-deficient mice are susceptible to many serious diseases, which indicates the potential uncontrolled side effects of direct targeting of ATG4B." (PMID 38803355, 2024). "Autophagy related protease 4B (ATG4B) is a protease required for autophagy processing, which is strongly implicated in cancer progression." (PMID 37038218, 2023). "ATG4B serves as a tumor promoter in various types of cancers, where elevated expression is associated with worsened survival of cancer patients." (PMID 37038218, 2023). "Per the findings, YY1 was identified as a crucial transcriptional activator of cancer autophagy-related genes and promoted the proliferation and aggressiveness of cancer cells associated with enhanced ATG4B-mediated autophagy." (PMID 37724907, 2023). "The association of ATG4B with cancer has recently gained much attention, due to its key role in the regulation of autophagy and cell differentiation." (PMID 32532053, 2020). "Members of the ATG4 and the LC3/GABARAP family have been implicated in various diseases including cancer, and targeting the ATG4B protease has been suggested as a potential therapeutic anti-cancer strategy." (PMID 30443548, 2018). "ATG4B has been implicated in several diseases, including pulmonary fibrosis, lung endotoxemia/sepsis, colitis, ischemia/reperfusion, Huntington’s disease, and various forms of cancer." (PMID 31878323, 2019). "Furthermore, we found hotspot mutations in the arginine-rich stretch in MAP1LC3A resulting in reduced cleavage of MAP1LC3A by ATG4B both in vitro and in vivo, suggesting a functional implication of this gene mutation in cancer development." (PMID 27256984, 2016). "More and more evidence indicates the overexpression of ATG4B in various cancer types, which makes it a prospective candidate for anticancer therapeutic strategies." (PMID 40444035, 2025). "Due to the fact that ATG4B expression is elevated in various cancers and promotes cancer cell growth, ATG4B inhibitors have been developed and investigated in pre-clinical studies." (PMID 41275290, 2025). "The role of ATG4B in cancer cells is well documented; however, studies on ATG4B in hematological malignancies are limited." (PMID 41275290, 2025). "The ATG4 family (ATG4A, ATG4B, ATG4C, and ATG4D) encodes proteases essential for autophagy, a process implicated in cancer progression and drug resistance." (PMID 40883962, 2025). "Inhibitors such as Z-FA-FMK, FMK-9a, NSC185058, and S130 have shown significant inhibition of ATG4B, with promising results in preclinical cancer models." (PMID 39456967, 2024). "ATG4B, which is highly expressed in cancer and contributes to metastasis and drug resistance, is considered a potential anticancer target." (PMID 39456967, 2024). "Gain- and loss-of-function assays were employed in the scrutiny of the biological effects of the ALKBH5/YY1/ATG4B axis on cancer cell proliferation and invasion abilities in vitro." (PMID 37724907, 2023). "The expression of ATG4B in GC cells was assessed using RT-qPCR, resulting in significantly highly expressed ATG4B in cancer cells than in normal GES-1 cells." (PMID 37724907, 2023). "Emerging studies also indicate that ATG4B silencer or inhibitor reduces cell proliferation and metastatic features of cancer cells." (PMID 37038218, 2023). "The literature reports emerging studies that are focused on the development of several ATG4B inhibitors to block cancer cell proliferation, mobility, and drug resistance." (PMID 37038218, 2023). "Cancer cells with ATG4B knockouts have suppressed autophagy and activated AMPK for cell cycle arrest." (PMID 37790613, 2023). "Silencing ATG4B attenuated cell growth, mobility, and synergized cancer cells to chemotherapeutic drugs." (PMID 37038218, 2023).
cancer (continued). "Since ATG4B and its proteolytic activity are involved in the autophagy machinery and proliferation of cancer cells, the clinical correlation of ATG4B gene expression with CRC patients was initially analyzed according to TCGA database." (PMID 37038218, 2023). "In line with the effect of ATG4B silencing in cancer cells, most of ATG4B inhibitors exerted anticancer activity via suppressing autophagy process." (PMID 35184132, 2022). "The development of novel and potent ATG4B inhibitors with different scaffolds are still needed to explore the therapeutic potential of targeting ATG4B in cancer." (PMID 35184132, 2022). "Previous researches revealed increased expression of ATG4B in lung cancer cells, but its prognostic value for different cancers is poorly understood." (PMID 35600411, 2022). "Recently, several ATG4B inhibitors were discovered and used to explore the physiological functions of ATG4B in cancers." (PMID 35184132, 2022). "Numerous studies have shown that regulation of Atg4B expression can affect the occurrence and development of cancer." (PMID 36457747, 2022). "In a word, ATG4B is a core autophagy-related protein and shows promising direction for cancer therapy by inhibiting autophagy." (PMID 36034776, 2022). "Recent studies have shown that CRNDE affects the expression and/or activity of some miRNAs as a sponge, while several miRNAs have impact on the stability of ATG4B mRNA in various cancer cells." (PMID 34409031, 2021). "Given the important role of this enzyme in autophagy and the encouraging results following ATG4B inhibition in several tumors, ATG4B is becoming increasingly attractive as a therapeutic target for cancer." (PMID 34868951, 2021). "Accordingly, ATG4B is a potential anti-cancer target and a valid alternative to anti-lysosomal therapy due to its role in LC3 processing and autophagosome formation." (PMID 34868951, 2021). "Autophagy is closely related to the growth and drug resistance of cancer cells, and autophagy related 4B (ATG4B) performs a crucial role in the process of autophagy." (PMID 34409031, 2021). "A tremendous amount of reports suggest that ATG4B expression is elevated in various kinds of cancer, indicating that ATG4B is a potential anticancer target." (PMID 34031264, 2021). "Recent studies suggest that ATG4B is a potential biomarker and vital in cancer therapy through the regulation of autophagy." (PMID 33925460, 2021). "Recent studies have indicated that lysosome and autophagy related 4B cysteine peptidase (ATG4B) are two promising targets in autophagy for cancer therapy." (PMID 32532053, 2020). "Our results suggest that compared to XOS00163, XOS00201, and XOS00207, 163N shows a slightly lower activity on ATG4B, but has a stronger anti-cancer effect." (PMID 32532053, 2020). "In this review, we address the central roles of ATG4B in the autophagy machinery and in targeted cancer therapy." (PMID 31083460, 2019). "In this review, we highlight some of the recent advances in our understanding of the role of ATG4B in autophagy and its relevance to cancer, and perform a critical evaluation of ATG4B as a druggable cancer target." (PMID 31878323, 2019). "Here, we will perform a critical appraisal of ATG4B as drug target in cancers and discuss tools and reagents available for drug development." (PMID 31878323, 2019). "The cysteine protease ATG4B is a potential anti-cancer target due to its roles in the regulation of autophagy." (PMID 31083460, 2019). "The oncogenic role of ATG4B in cancers has been reported previously in cell culture, tumor xenograft models, and even in clinical settings." (PMID 31771238, 2019). "Several key findings were made that provide strong evidence that targeting ATG4B in PDAC is a potential anti-cancer strategy." (PMID 31878323, 2019). "A high expression level of ATG4B seems to be connected with the progression of tumor as well as with cancer therapy resistance." (PMID 31083460, 2019).
cancer (continued). "An increasing amount of evidence suggests that ATG4B expression is elevated in certain types of cancer, implying that ATG4B is a potential anticancer target." (PMID 31083460, 2019). "ATG4B promotes cell cycle progression from G1 phase to S phase transition, drug resistance, and stemness in cancer cells." (PMID 31771238, 2019). "In this study, we exploited edible medicinal plants to screen for potential ATG4B inhibitors and determine their effects in cancer." (PMID 31159487, 2019). "Growing evidence has shown that ATG4B is involved in certain physiological and pathological tumor microenvironments through affecting the autophagy process, and ATG4B has gained much attention to be a potential drug target for cancer therapy." (PMID 31083460, 2019). "The roles of ATG4B in cancer and other diseases appear to be context dependent but are still not well understood." (PMID 30076329, 2018). "Because of the critical role of ATG4B in the autophagy process, an inhibitor of this protease has been proposed as a promising tool for monitoring the treatment not only of cancers but also of other diseases." (PMID 30374741, 2018). "ATG4B appears to act as a positive regulator of proliferation in some cancer types, although the roles of ATG4B and the effects of ATG4B inhibition are cell type, treatment, and context-dependent." (PMID 27556700, 2016). "Tioconazole (TCZ), an antifungal drug, is able to occupy the active sites of autophagy-related proteases autophagy related 4A (ATG4A) or autophagy related 4B (ATG4B), and directly block their enzymatic activity 58, thus diminishing autophagic flux in cancer cells under stress conditions." (PMID 41510169, 2026). "Recently, an important connection between ATG4B and the progression of cancer has been observed." (PMID 40444035, 2025). "Finally, our study underscores the need for further exploration of the various roles of ATG4B to fully understand its implications in cancer biology and its potential as a therapeutic target." (PMID 40788108, 2025). "Interestingly, a previous study showed that Atg4b knockout mice were viable and appeared normal in a battery of screening tests, which supports the idea that ATG4B is an attractive target for cancer treatment." (PMID 41275290, 2025). "In addition, phosphorylation of ATG4B at Ser 383/392 increases its protease activity, which is involved in cancer cell growth." (PMID 37038218, 2023). "Collectively, this study found that YY1 was regulated by ALKBH5 and YTHDF1-mediated m6A modification and served as an autophagy-dependent tumor driver to accelerate cancer progression through ATG4B transactivation, providing an exploitable therapeutic target for GC." (PMID 37724907, 2023). "Gene silencing of ATG4B, or, inhibiting ATG4B activity diminishes cancer cell viability and sensitizes cancer cell to chemotherapeutic drugs in vitro and in vivo suggesting ATG4B might play a role as tumor promoter." (PMID 37038218, 2023). "Taken together, Ebselen could be a promising and optimizable ATG4B inhibitor for related treatment of autophagy and cancers." (PMID 36539845, 2022). "Therefore, S130 is an effective pharmacological agent to combine with ATG4B in autophagy for the treatment of cancer." (PMID 36034776, 2022). "Besides, another study found that inhibition of autophagy by knocking down ATG7 or expressing dominant negative ATG4B in cancer cells resulted in a significant increase in the number of CD8+ T cells infiltrating in pancreatic tumors." (PMID 35600411, 2022). "Therefore, ATG4B is a requisite enzymatic component in the autophagy process and is becoming increasingly attractive target for cancer therapy." (PMID 36034776, 2022). "Several studies indicated that ATG4B inhibition might be helpful to overcome drug resistance; however, the pharmacological roles of ATG4B in cancer metastasis remained unknown." (PMID 35184132, 2022).
cancer (continued). "Since accumulating studies showed that autophagy inhibitors might improve the effects of chemotherapy in various cancer types, we wondered whether ATG4B inhibitors have the same function in GCa." (PMID 35184132, 2022). "To date, increasing evidences confirm that ATG4B is overexpression in cancer cells, indicating that the ATG4B inhibition may be an effective approach for cancer treatment." (PMID 36034776, 2022). "Although SNVs and RNA expression levels of ATG4B are not detected to be associated with cancer, the lower DNA methylation level of ATG4B is statistically correlated with a higher survival rate, supporting its oncogenic role in tumorigenesis." (PMID 34059679, 2021). "Several studies have demonstrated that ATG4B plays an important role in various cancers." (PMID 34868951, 2021). "Importantly, depletion of ATG4B also sensitized CML cancer stem cells to imatinib treatment, which indicates that inhibiting autophagy in combination with imatinib would have therapeutic potential in the treatment of CML." (PMID 32195258, 2020). "ATG4B agonists have also been proposed to be beneficial for anti-cancer strategies." (PMID 31878323, 2019). "Recent studies have shown that the knockdown of ATG4B can suppress cancer cells." (PMID 31159487, 2019). "The proteolytic activity of ATG4B is involved in cancer cell malignancy." (PMID 31771238, 2019). "Specifically, we discuss how pharmacologically inhibiting ATG4B can benefit cancer therapies." (PMID 31083460, 2019). "Due to the key role of ATG4B in autophagy process, ATG4B has attracted a great level of interest in the field of autophagy research and ATG4B inhibitors have been proposed as a potentially therapeutic approach for not only cancers but also other human diseases." (PMID 31083460, 2019). "Altogether, these data demonstrate that ATG4B could be a suitable therapeutic target for treating cancers." (PMID 31083460, 2019). "Thus, the aim of this study was to screen different Formosan plants extracts for potential inhibitors against ATG4B and/or autophagy, as a starting point for cancer therapy." (PMID 31159487, 2019). "Paradoxically, both agonists and antagonists of ATG4B could have therapeutic significance in cancer." (PMID 31083460, 2019). "ATG4B expression and activation are crucial for cancer cell proliferation and invasion." (PMID 31771238, 2019). "As such ATG4B has been considered as a potential therapeutic target for cancers." (PMID 31083460, 2019). "In addition to these lysosome inhibitors, other autophagy related targets such as ULK1, VPS34, BECN 1 and ATG4B have also been targeted by small molecule inhibition for cancer chemotherapy." (PMID 31083460, 2019). "Due to its central enzymatic roles in the autophagy process, the cysteine protease ATG4B became one of the autophagy proteins being pursued as a potential therapeutic target, but little is known about its prognostic value in different cancers." (PMID 28696368, 2017). "Moreover, previous reports indicated that Atg4B can be a potential biomarker and considered a more readily usable target of cancer therapy in autophagic machinery." (PMID 26221173, 2015). "Hence, inhibition of ATG4B nuclear localization could provide new opportunities for cancer prevention and therapy." (PMID 40788108, 2025). "Besides, we proposed a novel strategy to inhibit ATG4B and ATG4B-induced cancer progression." (PMID 38803355, 2024). "Furthermore, fruit extracts of T. terrestris extracted in acetone and methanol have also shown to negatively affect the proliferation, growth, migration, and invasion of cancer cells by targeting the cellular autophagy protease ATG4B (autophagin-1) to block autophagy pathway." (PMID 37631032, 2023). "Perhaps then, ATG4B may play its role as a tumor promoter in cancer." (PMID 37038218, 2023).